FBXO28 (F-box protein 28)
Description:
Substrate-recognition component of the SCF (SKP1-CUL1-F-box protein)-type E3 ubiquitin ligase complex, promoting ubiquitination and proteasomal degradation of specific target proteins including TOP2A, RAB27A or itself. Regulates topoisomerase IIalpha/TOP2A decatenation activity and plays an important role in maintaining genomic stability. Plays a role in lipid metabolism and inflammation through the ubiquitinated degradation of RAB27A (By similarity). Strongly regulates beta-cell survival without having any significant independent effect on insulin secretion. Plays an essential role in spindle morphology and actin-based spindle migration probably through the ARPC2/ARP3 signaling pathway (By similarity).
Synonyms: CENP-30; KIAA0483; FLJ10766; Fbx28; DEE100
Tractability: PROTAC: ubiquitination databases record sites on it; its protein half-life has been measured.
Gene: Protein-coding gene on chromosome 1 (224,114,111 to 224,162,047, forward strand). Ensembl gene ENSG00000143756.
Subcellular location: Chromosome, centromere, kinetochore; Nucleus; Chromosome
Subcellular location (Human Protein Atlas): Nucleoplasm; Focal adhesion sites
Gene Ontology:
Molecular function: identical protein binding; protein binding; ubiquitin-like ligase-substrate adaptor activity
Biological process: proteasome-mediated ubiquitin-dependent protein catabolic process; protein polyubiquitination; SCF-dependent proteasomal ubiquitin-dependent protein catabolic process
Cellular component: cytoplasm; kinetochore; nucleoplasm; nucleus; chromosome; SCF ubiquitin ligase complex
Genetic constraint (gnomAD): Loss-of-function variants: 7 observed, 30.12 expected, observed/expected ratio (o/e) 0.23, 90% interval 0.13 to 0.44. The upper end of that interval is the gene's LOEUF score, 0.44, which puts it in group 1 of 6, group 1 being the genes least tolerant of losing a copy. Missense variants: 339 observed, 432.4 expected, observed/expected ratio (o/e) 0.78, 90% interval 0.72 to 0.86. Synonymous variants: 166 observed, 164.61 expected, observed/expected ratio (o/e) 1.01, 90% interval 0.89 to 1.15.
Homologues: Orthologues: chimpanzee FBXO28 (100% identical), macaque FBXO28 (99% identical), pig FBXO28 (97% identical), rabbit FBXO28 (96% identical), dog FBXO28 (96% identical), rat Fbxo28 (95% identical), mouse Fbxo28 (95% identical), guinea pig FBXO28 (94% identical), tropical clawed frog fbxo28 (77% identical), zebrafish fbxo28 (66% identical), Drosophila melanogaster dmpd (32% identical), Drosophila melanogaster pall (28% identical).
Diseases named in the same sentence as FBXO28 in open-access papers:
FBXO28 is named in the same sentence as 25 diseases in open-access papers, as found by Europe PMC text mining. Sharing a sentence is not in itself a finding about the gene and the disease. The quoted sentences say what the papers report.
breast carcinoma (7 papers, 2013 to 2025). "The rs10916264 A-allele correlates with increased expression of FBXO28, which in turn was associated with poor breast cancer survival in the Kaplan-Meier Plotter database." (PMID 28179588, 2017). "This suggests that expression and phosphorylation of FBXO28 may be linked to clinical outcome in breast cancer." (PMID 23776131, 2013). "We conclude that FBXO28 expression is positively correlated with increased expression of a subset of genes that are preferentially targeted by MYC in association with p300 in human breast cancer." (PMID 23776131, 2013). "Importantly, we find that FBXO28 expression and phosphorylation to be strongly associated with poor prognosis and worse overall survival (OS) in human breast cancer." (PMID 23776131, 2013). "Importantly, we found a strong association between poor overall-, breast-cancer specific- and relapse-free-survival and high FBXO28 protein levels in two independent cohorts, and in multivariate analysis, expression and phosphorylation of FBXO28 were independent predictors of poor survival." (PMID 23776131, 2013). "CDK1 can be considered an optimal CDK target for breast cancer treatment, promoting MYC-driven transcription and tumorigenesis through mediated ubiquitin ligase activation of FBXO28 and predicting poor survival in breast cancer." (PMID 39991589, 2025). "The IHC analysis displayed that FBXO28 and its phosphorylation are strong and predicted a poor prognosis in breast cancer." (PMID 35046938, 2021). "To validate and extend these results, we performed TMA analysis of FBXO28 expression and phosphorylation in an additional large and independent breast cancer cohort (cohort 3, n = 498)." (PMID 23776131, 2013). "One of the major discoveries in this study is the result that high expression and phosphorylation of FBXO28 positively correlate with several adverse clinicopathological characteristics and poor outcome in breast cancer (7 and 8)." (PMID 23776131, 2013). "Moreover, the FBXO28 inhibited SNAI2 protein level was fully rescued by treatment with a proteasome inhibitor MG132 in the Huh7 cells as well as human breast cancer MDA-MB-231, lung cancer NCI-H460 and osteosarcoma Saos-2 cell lines." (PMID 37596321, 2023). "Finally, in human breast cancer, high FBXO28 expression and phosphorylation are strong and independent predictors of poor outcome." (PMID 23776131, 2013). "To directly evaluate the potential association between FBXO28 expression and the expression of MYC target genes in breast cancer, we extracted gene expression data representing 327 clinical breast cancer specimens (; GSE6532) and identified 102 genes highly related to FBXO28 expression." (PMID 23776131, 2013). "Importantly, when analysed by multivariate analysis, the NF of FBXO28 retained its prognostic significance as an independent predictor of poor OS in breast cancer (HR 3.19 [1.22–8.33], p = 0.018)." (PMID 23776131, 2013). "Importantly, both FBXO28 expression (NI) and phosphorylation (NF) were found to be independent predictors of worse outcome by multivariate analysis also in this cohort of breast cancer patients." (PMID 23776131, 2013). "Indeed, searching the Oncomine database verified that FBXO28 expression was significantly higher in primary breast cancers relative to normal breast tissue in multiple expression profiling studies." (PMID 23776131, 2013). "In luminal-types breast carcinoma, FBXO16 was inclined to over-express in luminal A and B groups and FBXO28 was a potential up-regulated biomarker of luminal B groups." (PMID 33622332, 2021). "This lends credence to the idea that genetic variation at this locus influences breast cancer survival through regulation of one or both of the genes TP53BP2 and FBXO28." (PMID 28179588, 2017).
breast carcinoma (continued). "FBXO28 is also found to be upregulated in breast cancer (BC) and pancreatic ductal adenocarcinoma (PDAC), and high FBXO28 expression might serve as a poor prognostic factor for BC and PDAC." (PMID 37596321, 2023).
Intellectual disability (3 papers, 2017 to 2024). "For example, FBXO28 variants cause developmental and epileptic encephalopathy, and with severe intellectual disability." (PMID 38267923, 2024). "WDR26 and FBXO28 are located within the 1q41-q42 deletion syndrome critical region, a rare cause of intellectual disability, seizures, facial dysmorphia, and multiple anomalies." (PMID 36980980, 2023). "FBXO28 is characterized by an approximately 40-amino acid F-box motif and was reported to contribute to intellectual disability, seizures and a dysmorphological phenotype in patients with 1q41q42 microdeletion syndrome." (PMID 28286461, 2017).
breast tumor (2 papers, 2013 to 2017). "Our eQTL analyses of METABRIC gene expression data indicate that rs10916264 and its tagging SNPs associate with the expression of FBXO28 also in breast tumor tissue (p = 0.0016)." (PMID 28179588, 2017). "However, high FBXO28 levels were also found to be associated with poor prognosis in particular patient subgroups, including low proliferative luminal A tumours and in highly proliferative (high Ki-67 levels), poorly differentiated breast tumours, presumably tumours with hyperactivation of MYC." (PMID 23776131, 2013). "We also observed substantial variation in the levels of phosphorylated FBXO28 in these breast tumours." (PMID 23776131, 2013). "FBXO28 immunoblot analysis in a cohort of primary breast tumour specimens (cohort 1, n = 72), demonstrated a statistically significant correlation between high FBXO28 protein levels and poorly differentiated breast tumours (p = 0.039)." (PMID 23776131, 2013). "We next evaluated FBXO28 phosphorylation by immunohistochemistry (IHC) analysis performed on tissue microarrays (TMAs) the pS344-FBXO28 specific antibody in a second and independent cohort of 144 breast tumour specimens (cohort 2)." (PMID 23776131, 2013). "Indeed, the NF of phosphorylated FBXO28 clearly separated breast tumours according to OS, as evaluated by log-rank analysis of Kaplan–Meier curves." (PMID 23776131, 2013).
pancreatic cancer (2 papers, 2023). "However, the potential function of FBXO28 in pancreatic cancer (PC) and its molecular mechanism remain unclear." (PMID 37348029, 2023).
pancreatic ductal adenocarcinoma (2 papers, 2023 to 2024). An infiltrating adenocarcinoma that arises from the epithelial cells of the pancreas. "By a comprehensive analysis, FBXO28 was found to be highly expressed in pancreatic ductal adenocarcinoma." (PMID 38267923, 2024).
developmental delay (1 paper, 2023). "The neurodevelopmental phenotype (i.e., developmental delay and brain imaging abnormalities) observed in our patient aligns closely with reported cases of 1q41q42 deletion encompassing FBXO28 and observations associated with pathogenic FBXO28 coding variants." (PMID 37761828, 2023). "Mutations in FBXO28 are associated with developmental and epileptic encephalopathy-100 (OMIM:619777), a severe neurologic disorder characterized by global developmental delay and the onset of variable types of seizures in the first months or years of life." (PMID 37761828, 2023).
Encephalopathy (1 paper, 2023). Encephalopathy is a term that means brain disease, damage, or malfunction. "Notably, all but two of the identified pathogenic sequence variants in FBXO28 encephalopathy are located close to each other in the final exon of FBXO28." (PMID 37761828, 2023).
glioblastoma (1 paper, 2022). The most malignant astrocytic tumor (WHO grade IV). "Our finding that FBXO28 is downregulated in glioblastoma patients is in line with this." (PMID 36115843, 2022). "Interestingly, gene expression profiling data from glioblastoma patients shows that FBXO28 is actually downregulated in glioblastoma compared with normal brain, and low FBXO28 expression correlates with poor survival." (PMID 36115843, 2022).
hepatocellular carcinoma (1 paper, 2023). A malignant tumor that arises from hepatocytes. "Here, we report that FBXO28 is a critical negative regulator of migration, invasion and metastasis in human hepatocellular carcinoma (HCC) in vitro and in vivo." (PMID 37596321, 2023).
microdeletion syndrome (1 paper, 2023). "Furthermore, our study provides new evidence supporting the hypothesis that FBXO28 plays an important role in the pathogenesis of chromosome 1q41q42 microdeletion syndrome, and it also suggests the potential functional importance of the 3′ UTR region in FBXO28." (PMID 37761828, 2023).
ovarian carcinoma (1 paper, 2024). A malignant neoplasm originating from the surface ovarian epithelium. "The association between FBXO28 and ovarian cancer prognosis was analyzed using Kaplan‒Meier survival analysis." (PMID 38267923, 2024). "We found that a higher expression level of FBXO28 was associated with poor prognosis in ovarian cancer patients." (PMID 38267923, 2024). "The present study demonstrated that FBXO28 expression was associated with poor prognosis in ovarian cancer patients and that the upregulation of FBXO28 was positively correlated with the proliferation, migration and invasion capacity of ovarian cancer cells." (PMID 38267923, 2024). "Kaplan‒Meier survival analysis indicated that FBXO28 expression levels could be associated with prognosis of ovarian cancer." (PMID 38267923, 2024). "The survival curve of FBXO28 levels and ovarian cancer indicated that FBXO28 expression levels could be linked to prognosis of ovarian cancer." (PMID 38267923, 2024). "Hence, it is hard to conclude that the expression of FBXO28 was associated with ovarian cancer prognosis, which needs further exploration whether FBXO28 could be a predictor of prognosis of ovarian cancer patients." (PMID 38267923, 2024). "Analysis of the TCGA and GTEx cohorts showed that the FBXO28 mRNA level was lower in normal ovarian tissue samples than in ovarian cancer tissue samples." (PMID 38267923, 2024). "Our study demonstrated that FBXO28 facilitates malignant behavior of ovarian cancer cells via activation of TGF-b1 /SMAD2/3 pathway." (PMID 38267923, 2024). "The upregulation of FBXO28 promoted the viability, proliferation, migration and invasion of ovarian cancer cells." (PMID 38267923, 2024). "Subsequently, we analyzed the expression of the FBXO28 protein in ovarian cancer tissues and human normal ovarian tissues by immunohistochemistry." (PMID 38267923, 2024). "The expression levels of the FBXO28 protein in ovarian cancer tissues and normal ovarian tissues were measured via immunohistochemical staining." (PMID 38267923, 2024). "We found that downregulation of FBXO28 inhibited the viability of SKOV3 and A2780 cells, while overexpression of FBXO28 promoted ovarian cancer cell viability." (PMID 38267923, 2024). "We found that FBXO28 was expressed at a greater level in ovarian cancer cells than in normal ovarian IOSE80 cells." (PMID 38267923, 2024). "The results showed that the expression level of FBXO28 in ovarian cancer tissue was greater than that in normal ovarian tissue (P < 0.05)." (PMID 38267923, 2024). "Next, we investigated whether a change in FBXO28 expression affects the migration and invasion ability of ovarian cancer cells." (PMID 38267923, 2024). "Our study not only confirmed that FBXO28 may be associated with the prognosis of ovarian cancer patients, but also analyzed the related molecular mechanisms of FBXO28-mediated ovarian carcinogenesis, helping to elucidate the role of FBXO28 in ovarian cancer." (PMID 38267923, 2024). "Therefore, FBXO28 exerts its oncogenic function partly by targeting the TGF-b1/p-Smad2/3 axis in ovarian cancer." (PMID 38267923, 2024). "Therefore, the in vivo results further supported that FBXO28 promoted oncogenesis in ovarian cancer." (PMID 38267923, 2024). "Western blotting was used to determine the level of FBXO28 expression in ovarian cancer cells." (PMID 38267923, 2024). "Thus, our data suggested that FBXO28 participates in promoting the migration and invasion of ovarian cancer cells." (PMID 38267923, 2024). "Taken together, due to the critical oncogenic role of FBXO28 in ovarian cancer, our study indicated that targeting FBXO28 by its inhibitors could be a promising approach for the treatment of ovarian cancer." (PMID 38267923, 2024). "Therefore, in the present study, we aim to explore the functions of FBXO28 on cell proliferation, migration and invasion in ovarian cancer." (PMID 38267923, 2024).
ovarian carcinoma (continued). "Moreover, the CCK-8 assay results showed that overexpression of TGF-b1 abolished the FBXO28 knockdown-induced decrease in ovarian cancer cell viability." (PMID 38267923, 2024). "Moreover, in animal experiments, FBXO28 conditional transgenic or knockout mouse models are ideal tools for determining the role of FBXO28 in ovarian cancer." (PMID 38267923, 2024). "Notably, we observed that the overexpression of TGF-b1 could partially eliminate the inhibitory effects of FBXO28 knockdown on the proliferation, migration and invasion of ovarian cancer cells." (PMID 38267923, 2024). "However, whether FBXO28 can regulate TGF-b1 during ovarian cancer progression is unclear." (PMID 38267923, 2024). "Hence, FBXO28 could affect ovarian cancer progression through the TGF-b1 signaling pathway." (PMID 38267923, 2024). "In addition, the expression of the FBXO28 protein in normal ovarian IOSE80 cells and ovarian cancer cell lines, including the A2780, SKOV3 and OVCAR3 cell lines, was detected by Western blotting." (PMID 38267923, 2024). "Moreover, we plan to determine whether FBXO28 can promote ovarian oncogenesis via regulation of TGF-b1 and SMAD2/3 signaling pathways in ovarian cancer." (PMID 38267923, 2024). "Therefore, FBXO28 may regulate the expression levels of EMT factors through the TGF-b1 signaling pathway and affect the progression of ovarian cancer." (PMID 38267923, 2024).
ovarian tumor (1 paper, 2024). "The difference in FBXO28 mRNA expression between normal ovarian tissues and ovarian tumor tissues was obtained from The Cancer Genome Atlas (TCGA), and Genotype-Tissue Expression (GTEx) cohorts." (PMID 38267923, 2024). "The results showed that the expression of the FBXO28 protein in ovarian tumor tissues was greater than that in normal ovarian tissues." (PMID 38267923, 2024). "Compared with that in normal ovarian tissues or cell lines, the expression of FBXO28 was greater in ovarian tumor tissues or tumor cells." (PMID 38267923, 2024).
Seizure (1 paper, 2023). A seizure is an intermittent abnormality of nervous system physiology characterized by a transient occurrence of signs and/or symptoms due to abnormal excessive or synchronous neuronal activity in the brain. "Seizures are present in over 75% of patients 2 years old or younger who harbor deletions in an ~300 kb critical region containing FBXO28, and all patients carrying pathogenic FBXO28 sequence variants experience seizures, with age of onset ranging from 8 months to 5 years." (PMID 37761828, 2023).